MGMT (O-6-methylguanine-DNA methyltransferase)
Diseases named in the same sentence as MGMT in open-access papers (continued):
Sharing a sentence is not in itself a finding about the gene and the disease.
tumor (continued). "This analysis only includes imaging interpretation, while sometimes tumor board decisions may depend on other factors including tumor genetics (such as IDH, MGMT, and 1p19q status), radiation treatment plans, or patient functional status, which were not fully explored within this analysis." (PMID 37104141, 2023). "Moreover, in case of relapse, a second resection is not regularly performed and the MGMT status is usually not known on the recurrent tumor." (PMID 37190181, 2023). "Given the undetectable levels of expression of MGMT in the ACTH secreting tumor (evaluated in 2014 and 2015 lesions), MGMT would not contribute to TMZ resistance and it would probably be the short TMZ cycle (only 3 months) the key point of tumor regrowth from the highly proliferative remnant." (PMID 35928898, 2022). "Furthermore, we found that the high-risk group was obviously correlated with several risk factors, such as older age, higher tumor grades, IDH wild type, 1p19q noncodel, and MGMT unmethylation status." (PMID 35647198, 2022). "Targeted silencing of MGMT in pre-radiated tumor sites using our novel approach, without measurable MGMT silencing in non-radiated sites, may limit systemic toxicities associated with prior approaches to deplete MGMT in combination with temozolomide." (PMID 33850305, 2022). "Besides different treatment regimens for rGBM, no prognostic factor (including age, sex, KPS, recurrent tumor volume, IDH1 mutation status, and MGMT promotor methylation status) has been reported to exert a significant impact on OS and PFS." (PMID 36046037, 2022). "Interestingly, this downregulation of MGMT was further enhanced (80–98%) by the addition of MTIC, suggesting that Cerebraca wafer implantation, followed by TMZ administration, killed the residual tumor cells." (PMID 35205800, 2022). "However, assumptions should not be based on the methylation analysis of the primary tumor alone as the MGMT promoter methylation can frequently change." (PMID 35563629, 2022). "However, in tumor cells without MGMT, which are classified as promoter-methylated, O6MeG remains and accumulates following repeated treatments in the tumor cell DNA." (PMID 35785203, 2022). "As shown in the plot, we found that almost all patients from the high-risk subgroup had the C4 immune subtype, tumor grade 3 or 4, and high mortality, with a higher proportion of poor prognostic factors such as IDH wild type, 1p19q non-codeletion, and MGMT unmethylation." (PMID 35719998, 2022). "This is evidenced by modest radiological responses to single agent temozolomide (TMZ) or dacarbazine in MGMT methylated or protein negative tumours that do not characteristically respond when not biomarker selected (e.g. oesophageal or colorectal cancer (CRC) (9.4% ORR in oesophageal cancer)." (PMID 36050653, 2022). "Furthermore, the high-risk group was significantly correlated with several risk factors, including older age, higher tumor grade, IDH wild type, 1p19q noncodel, and MGMT unmethylation." (PMID 35647198, 2022). "In the TTFields therapy arm, patients whose tumors were MGMT promoter methylation status positive had a numerically extended OS (95% CI) of 10 months (6.0–13.9) vs 6.5 months (4.5–7.4) in patients with tumor-negative status; HR (95% CI) was 0.77 (0.46–1.30), (P = 0.322, log-rank test)." (PMID 36239858, 2022). "Furthermore, lowering oxygen tension in tumour spheroid cultures offers protection against TMZ toxicity, and the increased expression of MGMT in 5% GBM cultures could be a likely reason for the observed resistance." (PMID 36230775, 2022). "Notably, the m5CrLS group predicted prognosis was independent of age, WHO tumor grade, MGMT promoter status, and IDH status." (PMID 35309316, 2022). "Furthermore, tumor progression occurred with contrast-enhancing lesion and multiple masses during the third cycle of adjuvant TMZ treatment, implying that the tumor was perhaps refractory to TMZ, particularly with an unmethylated MGMT promoter." (PMID 33706745, 2021).
tumor (continued). "The lack of detailed tumour classification and documentation of prior therapy is a notable limitation of this trial, and the need for full characterisation in future trials, including MGMT methylation status, is recognised." (PMID 33623076, 2021). "The MGMT promotor status was not significantly correlated with edema to tumor ratio." (PMID 33868245, 2021). "In our study, unlike ECs, no tumor cells in GBM or PT tissue were stained for MGMT." (PMID 33562724, 2021). "The results of the stereometric analysis clearly showed that the cell density of MGMT-negative cells was higher in tumor samples compared to the PT area (p < 0.0001, two-sample Wilcoxon rank-sum, Mann–Whitney test; PT: median, 52.1; range, 0.54–92.4; GBM: median, 10.2; range, 0.0–76.5)." (PMID 33562724, 2021). "No such MGMT methylation-dependent tumor size difference was seen in the 19/20 co-gain group." (PMID 34199376, 2021). "Before proposing a prospective interventional clinical study, it is necessary to confirm the beneficial effect of the combined effect of MGMT methylation and moderate tumor vascularity, as well as the lack of benefit of temozolomide in patients with a highly vascular tumor." (PMID 34771583, 2021). "SFX-01 reduced tumor growth in subcutaneous xenografts in vivo, independent of the MGMT status." (PMID 34832864, 2021). "This could also indicate a higher apoptotic activity in tumor cells with EGFR-amplification regardless of the MGMT-methylation status." (PMID 34298788, 2021). "Thus, although extensive methylation in MGMT and SFRP2 has a similar feature in terms of association with CRC with KRAS mutations, all POLE-mutant tumours demonstrated extensive methylation in SFRP2, but no methylation in MGMT." (PMID 34034807, 2021). "Indeed, even the predictive value of MGMT promotor methylation with regards to tumor response to TMZ is not uncontroversial." (PMID 34485282, 2021). "GBMs with MGMT methylation on the other hand demonstrate left temporal lobe location and less diffusion restriction in addition to a larger proportion of the nonenhancing tumor." (PMID 34199376, 2021). "Additionally, a bifunctional DNA-targeting agent, dianhydrogalactiol, showed anti-tumor effect independent of MGMT and mismatch repair status." (PMID 34073837, 2021). "Furthermore, the effect of ROI information was investigated and the results indicated that using tumor ROI did not improve prediction accuracies for IDH and MGMT mutations in GBM patients." (PMID 34298824, 2021). "The aim of our study is to investigate whether MGMT promoter methylation is a phenomenon that is restricted to neoplasms in the CNS, or whether it could be detected in other non-neoplastic CNS pathologies as well." (PMID 33917711, 2021). "By contrast, VISTA is not statistically increased in MGMT methylated tumour cores compared with unmethylated tumour cores of GBMs (p = 0.153); MGMT methylated tumour core (11.94 [0.70]) and MGMT unmethylated tumour core (11.42 [0.77]) although mean normalised counts are increased." (PMID 33995529, 2021). "The tumor was negative for IDH1(R132) mutation and MGMT unmethylated." (PMID 33353026, 2020). "Second, nonattendance of the tumor-related variables, such as MGMT methylation status and isocitrate dehydrogenase-1 (IDH-1) and IDH-2, and local/systemic reactive proinflammatory cytokine/chemokine levels disallowed us to perform SII group-based analysis according to these biomarkers." (PMID 32565725, 2020). "Therefore, re-chemotherapy seems to be a treatment option for patients with methylated MGMT when tumor underwent non-local progression." (PMID 33251147, 2020). "The median survival was 16.9 and 16.4 months for patients whose tumor had unexpressed and moderate levels of Tim-3, respectively, whereas the median survival was 7.6 months for those who showed high levels of Tim-3 expression and MGMT promoter nonmethylation." (PMID 33041828, 2020).
tumor (continued). "However, we observed a trend indicating that the volume of FLAIR-T2 hyper-intensity, tumor mass, and necrosis, were greater in the tumors with non-methylated MGMT promoter." (PMID 32984040, 2020). "However, in that study, there was no information about the MGMT methylation status, number of relapse, or tumor dissemination." (PMID 33634023, 2020). "However, when OS2 was compared separately (median OS 471.817 days versus 243.267 days), there was a significant difference in the unmethylated MGMT patients, who appeared to benefit from a former treatment with TMZ after tumor recurrence and upgrading to sGBM (p<0.001)." (PMID 33392065, 2020). "Moreover, tumor mutations in isocitrate dehydrogenase (IDH) 1 and 2 was only available in later years (after 2010) and MGMT is not done in all patients." (PMID 32533126, 2020). "In one third a MGMT gene promoter methylation was detected, while 63% were unmethylated and 4% could not undergo analysis due to lack of sufficient tumor tissue." (PMID 32160197, 2020). "By excluding normal cells, the results of tumor MGMT methylation were not confounded." (PMID 32025325, 2020). "In this calculation, in case of unknown MGMT methylation status we always selected not methylated (accepting a negative bias for tumor that in reality were MGMT hypermethylated)." (PMID 31831026, 2019). "Residual tumor volume (RTV) and midline structures involvement were identified as independent prognostic factors of PFS while age, O-6-Methylguanine Methyltransferase (MGMT) status, Ki67 index, RTV and midline structures involvement represented independent predictors of OS." (PMID 31036031, 2019). "However, neither ADC-tumour nor ADC-oedema performed with satisfactory results for MGMT identification." (PMID 30039219, 2019). "A possible effect of alkylating agents on MGMT-methylated GISTs could thus have been missed, possibly due to an inappropriate selection of cases and a lack of proper evaluation of tumor response." (PMID 30616628, 2019). "On the other hand, MGMT hypermethylation has been largely reported in tissue and other samples from NSCLC patients and is found more frequently methylated in Stage III and IV tumors, which suggests an increased ability of proliferation and invasion of tumor cells." (PMID 31547177, 2019). "In 75% of cases, tumor progression was encountered after STR or biopsy, including in three patients with postoperative radio- or chemotherapy; nonetheless, recurrence was also observed in four patients after GTR, with all but one harboring MGMT promoter methylation." (PMID 31362435, 2019). "Tumor cells were negative for IDH mutation and positive for MGMT methylation status." (PMID 31929892, 2019). "Notably, patients with (MGMT meth) and without (MGMT unmeth) MGMT promoter methylation were comparable with respect to age, sex, tumor location, radiographic appearance and treatment at 1st diagnosis." (PMID 31362435, 2019). "In comparison, the one tumor obtained from M24 cells in TMZ-treated animals was MGMT-negative." (PMID 30274152, 2018). "The combination of alkylating agents with an MGMT inhibitor has failed in clinical trials for a simple reason; alkylating agents are more toxic to non-target tissues, especially bone marrow, than toward tumor cells." (PMID 29844863, 2018). "In both groups, high CD45, high CD4 count, high CD8 count, gender, receiving radiotherapy alone, TMZ therapy alone, salvage gamma knife (GKS) treatment, or tumor cells expressing IDH1 mutation, and MGMT methylation were all not significant prognostic factors under HR evaluation." (PMID 29910795, 2018). "In addition, MGMT promoter methylation status was only available for cells but not for tumor samples." (PMID 29755294, 2018). "Similar to the sellar recurrence, tumour cells were negative for MGMT and about 70% expressed MSH6." (PMID 28284009, 2017).
tumor (continued). "But DAPK promoter methylation had a similar frequency in the blood in GC and controls, these results suggested that promoter methylation of the ten tumor-related genes (p16, CDH1, RUNX3, MLH1, RASSF1A, p15, APC, GSTP1, Reprimo, and MGMT) may be potential biomarkers based-blood test for GC." (PMID 29100425, 2017). "As far as LEV is concerned, in 2010 Bobustuc hypothesized that AED may modulate O-6 methylguanine-DNA methyltransferase (MGMT), a DNA repair protein that has an important role in tumor cell resistance to alkylating agents, and LEV was reported as the most potent MGMT inhibitor among several AED." (PMID 28587680, 2017). "GH adenomas did not necessitate any further surgery so that tumor samples were not available.A change of MGMT immunoexpression pattern may be due to selection of more radio-resistant cell clones as shown in different cell lineages." (PMID 28900805, 2017). "Neither ATRX nor MGMT protein expression changed in 31 cases of recurrent tumours." (PMID 29026176, 2017). "Therefore, an integrated analysis was performed to evaluate the ability of 11 tumor-related genes (p16, CDH1, RUNX3, MLH1, RASSF1A, p15, APC, DAPK, GSTP1, Reprimo, and MGMT) promoter methylation test using blood samples as a feasible biomarker in GC diagnosis and screening." (PMID 29100425, 2017). "However, increased median methylation (~10×) of ADCY8, CDH8, and ZNF582, but not MGMT, was noted in the tumor cohort (N = 257) compared with the three normal samples." (PMID 27651839, 2016). "MGMT methylation was not correlated with tumor types, clinical stage, age status, H. pylori status." (PMID 27824946, 2016). "Indeed, treatment with BMP7 alone allows for delaying tumor development/progression without TMZ compared to untreatment or treatment with TMZ alone, suggesting that the anti-tumor activity of BMP7 is independent of MGMT status in GSC." (PMID 26546412, 2015). "This may have a bearing on TMZ resistance and could explain the failure of TMZ treatment in tumor cells with no MGMT expression." (PMID 26447477, 2015). "Genetic approaches for elucidation of mechanisms by which BMP7 downregulates MGMT, ABC efflux transporters, stemness, and EMT would further facilitate our understanding the process and ability to identify new treatment targets and strategies for preventing treatment resistance and tumor recurrence." (PMID 26546412, 2015). "In addition, analysis of MGMT promoter hypermethylation was also performed, and comparable promoter DNA hypermethylation was found in the anaplastic PXA samples as well as in the one grade II tumor further relapsing as an anaplastic PXA." (PMID 24650279, 2014). "In contrast to the DNA repair gene O6-methylguanine-DNA methyltransferase (MGMT), which has been found to be methylated in the macroscopic field of some CRCs, in our study epithelial SFRP1 hypermethylation was only present in areas closely localized to the tumor (NAT)." (PMID 25405986, 2014). "Therefore, we conclude that chronic vemurafenib treatment has no impact on MGMT, which is supported by our data obtained with tumor specimens." (PMID 25557167, 2014). "Furthermore, two out of the seven mice who were treated with IL MGMT-kB1 LODN demonstrated tumor regression by day 55 and no tumor recurrence was observed five months after the end of treatment." (PMID 25460932, 2014). "However, this conclusion was drawn from in vitro studies and, thus far, no clinically satisfactory assay for assessing MGMT protein in tumor tissues, including immunohistochemistry, has been reported." (PMID 23505468, 2013). "This makes it difficult to determine whether any MGMT positivity within the tumour is due to tumour cells or non-tumour cells." (PMID 24252243, 2013). "Double-labelling immunohistochemistry for MGMT and a cocktail of non-tumourous elements provides a "one look" method for determining whether tumour cell nuclei are MGMT-positive or MGMT-negative." (PMID 24252243, 2013).
tumor (continued). "Likewise, MGMT and TP73 exhibit hypomethylation in multiple tumor types." (PMID 23033966, 2012). "As an example patients with VAK score 2 and 3 (VAK-B class) having a poor survival and small benefit from multimodal therapy and favorable MGMT status, can be selected as candidates for new clinical trials rather than selecting the standard recurrent tumor patient group." (PMID 22870228, 2012). "The prognostic effect of MGMT promoter methylation status seems to be independent of resection, and patients with promoter methylation have the best prognosis, in particular when the entire contrast-enhancing tumor mass is removed." (PMID 22307805, 2012). "In 6/75 tumor samples we detected both MGMT promoter methylation and negative staining of MGMT." (PMID 23110891, 2012). "This phenomenon may be explained by intratumoral heterogeneity or by the detection of non-methylized MGMT promoter in tumor infiltrating lymphocytes, blood vessels or normal tissue." (PMID 23110891, 2012). "MGMT expression in the group of tumor samples with a hypermethylated promoter was statistically significantly lower compared to the group of tumors with no measured hypermethylation of the MGMT promoter." (PMID 22246327, 2012). "CIMP-high carcinomas were found in 34 cases (13.9%) and were more frequently associated with proximal tumor locations, poorly differentiated histology, mucinous histology, BRAF mutation, MGMT methylation, and MSI-high compared to CIMP-low/negative carcinomas (P < 0.05)." (PMID 21827707, 2011). "CIMP-high CRCs were identified in 34 cases (13.9%), and were significantly associated with proximal tumor location, poorly differentiated carcinoma, mucinous histology, and high frequencies of BRAF mutation, MGMT methylation, and MSI-high compared to CIMP-low/negative carcinomas." (PMID 21827707, 2011). "Recovery of MGMT activity after dosing may not mean that complete repair of O6-meG has taken place, at least not across the whole tumour." (PMID 19367283, 2009). "The comparison of the findings in the tumor tissue and in the peripheral blood from the same patient showed no RASSF1 or CDKN2A methylation in any of the peripheral blood samples, and only one sample positive for MGMT methylation; a T4N0 M0 (stage IVa) squamous cancer of the oral cavity." (PMID 19807915, 2009). "Another possible explanation for the difference between tumour and bone marrow is that tumour doubling times are such that the extension of MGMT inactivation to 10 or 14 days is still not sufficient to allow the two rounds of replication required for cell killing." (PMID 19367282, 2009). "Although numerous studies have proposed the strong linkage between MGMT expression and promoter hypermethylation of the gene, treatment with epigenetic compounds (5-aza-dC/VPA) was unable to increase MGMT protein levels in the transformed NHA cells or in cultured tumor cells." (PMID 17547775, 2007). "However, we showed that two-week-treatment with VPA inhibited tumor cell growth without increasing MGMT expression, suggesting potential clinical use although further preclinical studies are required." (PMID 17547775, 2007). "However, MGMT promoter methylation status was determined on tumour samples, and not in blood, thus indicating only an indirect correlation between MGMT and toxicity." (PMID 17024124, 2006). "There was no significant change in MGMT in tumor-derived breast or ovarian cells." (PMID 16026610, 2005). "In the light of this, some tumours that correspond to HCCs, 16C–28C, might be regarded as MGMT-negative because of the rapid degradation of the inactive form, although the gene might have been transcribed." (PMID 12592365, 2003). "The inactivated MGMT is not degraded but remains in an immunoreactive state in normal cells, whereas it is degraded rapidly via the ubiquitin proteolytic pathway in tumour cells." (PMID 12592365, 2003).